CCL2 (C-C motif chemokine ligand 2)
Diseases named in the same sentence as CCL2 in open-access papers (continued):
Sharing a sentence is not in itself a finding about the gene and the disease.
infection (continued). "The concentrations of chemokines, including CCL2, CCL5, and CXCL10, were all markedly reduced in the lungs of the AHCC-fed group at day 4 post infection (p < 0.05 or p < 0.01)." (PMID 37111440, 2023). "Monocyte chemoattractant protein 1 (MCP1), also known as CCL2, is one of the main chemokines that regulate monocyte recruitment in inflammation and infection." (PMID 36795489, 2023). "Accumulating evidence suggests that DMI and OI reduce the infection-induced inflammatory responses and the release of chemokines CXCL10 and CCL2." (PMID 36882813, 2023). "Outliers with elevated biomarkers observed in both pre-infection specimens included IL-1β (N=1 participant), suPAR (N=2), MCP-1/CCL2, sCD163, and CRP (N=3), TNFα (N=9) and/or leptin (N=23)." (PMID 37461626, 2023). "We observed that expression of inflammatory chemokine CCL2 and cytokine TNF-α increased in the brain of Irf7−/− during the course of infection." (PMID 37737190, 2023). "Increased expression of several cytokine/chemokine genes was observed in MC-HBOs after infection of ZIKA (IL6, IL1β, TNFα, and CCL2) and Dengue virus (IL1β and CCL2)." (PMID 36474001, 2023). "On the other hand, the expression of the chemokines CCL2 (P < 0.05), CX3CL1 (P < 0.05), and MCP-1 (P < 0.05) was significantly increased from day 3 post-infection." (PMID 37452371, 2023). "By day 2 after infection, significant elevations in the levels of interleukin-1β (IL-1β), TNF-α, IL-6, IFN-γ, IFNα, IFNβ, CXCL1, CCL2, and CCL5 were detected in the airways of influenza virus–infected mice." (PMID 37683004, 2023). "Before infection, the latent condition presented the chemokine panel with near-high levels of CXCL11 and mild or moderate levels of CXCL2, CCL4, CCL2, CCL1, and CXCL9." (PMID 37149713, 2023). "In line with mRNA expression changes, hypoxia markedly enhanced secretion of CCL2 and CXCL10 upon infection with SARS-CoV-2." (PMID 37377965, 2023). "Luminex analysis confirmed that remdesivir potently blocked SARS-CoV-2-induced cytokine release from ALI lung organoids at 48 hours post-infection, particularly evident for GCSF, IFNG, IL6, CXCL10, CCL2, and TNFA." (PMID 37205380, 2023). "Infection with both ZIKV lineages was characterized by a more proinflammatory and chemotactic profile, mediated by high levels of IL-1β, IL-6, TNF-α, CCL-2, CCL-3, CCL-7, CXCL8, IP-10, and VEGF." (PMID 37227282, 2023). "Both CCL2 and CCL3 play roles in monocyte chemotaxis to sites of inflammation and are known to be markers of severe infection with Mycobacterium tuberculosis." (PMID 36912627, 2023). "For a subset of patients, we assessed chemokines (CCL2, CCL3, and CCL7) in circulation and at the site of infection." (PMID 36752598, 2023). "Here, we also show that USUV and WNV BBB direct infection led to the release of potent chemoattractants such as CXCL10, CCL5 and CCL2 in vitro and in vivo." (PMID 36495563, 2023). "This was paralleled by an increase of chemokines (CCL-2, CCL-5, CXCL-10, IL-8) to attract immune cells to the site of infection, contributing to inflammation and tissue damage." (PMID 35788177, 2022). "Inflammatory monocytes can rapidly recruit and migrate to the region of injury or infection via C-C chemokine receptor type 2 (CCR2), C-C motif chemokine ligand 2 (CCL2), monocyte chemotactic protein-1 (MCP-1), and C-X-C motif ligand 10 (CXCL10)." (PMID 35669508, 2022). "It is reported that the infection of microsporidia Encephalitozoon cuniculi up-regulated expression of CCL1, CCL2, CCL3, CCL7 and other chemokines." (PMID 36015036, 2022). "SARS-CoV-2 infection also resulted in many cytokines and chemokines above baseline levels (all P < 0.05) throughout the infection, including IFN-γ, IL-1β, IL-4, IL-28, CXCL10, GM-CSF, LIF, CCL2, CCL7, MIP-1α, MIP-1β, RANTES, IFN-α, and IFN-β." (PMID 35634338, 2022). "Network analysis of serum mediators performed between 28 and 35 days after initial infection in the usual care study group shows persistent IFN-α2a, CCL11, and CCL2." (PMID 35397798, 2022).
infection (continued). "At day 6 after infection, expression levels of chemokines, including CXCL10 and CCL2 and CCL-3 were elevated by more than 300-fold." (PMID 35215199, 2022). "We analyzed the secretion or expression of different immunomediators (cytokines CCL2, CXCL8, TNF-α, and interferon-stimulated gene ISG15) at different times following infection of PAMS." (PMID 35019713, 2022). "In response to ocular HSV-1 infection, pro-inflammatory cytokines including IL-1, IL-6 and chemokines including CCL2, CCL3, CCL5, CXCL1, CXCL2, CXCL9, and CXCL10 are produced rapidly following infection by resident cells and infiltrating leukocytes." (PMID 36685562, 2022). "The overexpression of CCL2 and CCL20 genes in the THP-1 monocytic cells after infection with all Aeromonas spp." (PMID 35874671, 2022). "CCL2, also known as monocyte chemoattractant protein (MCP)-1 is an important regulator of monocyte and macrophage trafficking during infection and in the presence of inflammation." (PMID 35734179, 2022). "Similar to CCL2, CXCL10 is a potent attractant for monocytes, macrophages, T cells, NK cells, and dendritic cells at sites of tissue damage and infection." (PMID 35207538, 2022). "We have previously suggested that NK cells do not have a role in the direct control of the mycobacteria growth of Mtb, however, the contact between NKs and DCs during infection by M. bovis increases the production of IFN-γ, TNF-α, CCL2, CCL4, and CXCL8." (PMID 35456728, 2022). "Infections with the B.1.1.7, B.1.351, B.1.617.2, and MA10 viruses resulted in >100-fold increases in IL-6 and CCL-2 mRNA expression." (PMID 35746611, 2022). "The reduction of the mRNA expression of CCL2, CCL3, FGF, CXCL-10, and IFN-γ at the 9th-week post-infection reflects a downmodulation of the Th1 response by reducing the recruitment of inflammatory cells and HSCs to the granulomatous site." (PMID 35839247, 2022). "CCL2/MCP-1 is known to recruit monocytes, macrophages, activated T cells and natural killer (NK) cells to damaged tissue in the CNS after trauma, infection, or toxin exposure." (PMID 35885983, 2022). "Transcripts encoding cytokines and chemokines such as IL-1β (interleukin-1β), IL-18, IL-6, IFN-γ, IL-10, CCL2 (C-C motif chemokine ligand 2), CCL4 and CCL7 were also up-regulated in the lungs during infection." (PMID 34965194, 2022). "Lenti-Spike infection significantly increased the expression of inflammatory cytokines, including IL-1β, IL-6, and TNF-α, and chemokines, including CCL-2, CCL-3, CCL-4, and CXCL-10, whereas Lipo-hACE2 decoy significantly inhibited all these effects." (PMID 35401811, 2022). "There was mild decrease in the serum levels of IFN-γ, G-CSF, CCL2/MCP-1, and IFN-γ after dual species infections compared to sterile implants." (PMID 35203495, 2022). "Additionally, it is known that IL-6, CCL2 and IL-10 could be recognized as biomarkers for P. vivax acute infection phase, however, our study is unique in proposing a coefficient combining levels of four cytokines and chemokines as biomarkers for P. vivax severity." (PMID 36178979, 2022). "Deletion of 4b protein led to a significant reduction in the expression of IFNß, pro-inflammatory cytokines (IL-6 and IL-8) and chemokines (CCL2 and CXCL10) in relation to MERS-CoV-MA-WT infection." (PMID 36129908, 2022). "We confirmed a MDA5/STING-dependent upregulation of cytokine and chemokine genes after VACV∆C7L infection in AECII cells, including Ifnb1, Ccl2, Ccl7, Ccl4, Ccl5, and Cxcl10." (PMID 35351885, 2022). "Endothelial cells expressed IFN-β, IL-7, TNF, CCL2, and common inflammatory markers such as ICAM1 and VCAM1 after infection with IAV H5N1 as compared to the H1N1 virus." (PMID 36071442, 2022). "mRNA levels of several proinflammatory cytokines and chemokines (MDA5, CCL2, RIG-I, and CXCL10) were generally decreased at 1 or more times after infection, but only differences in RIG-I and MDA were statistically significant." (PMID 36378534, 2022).
infection (continued). "Proinflammatory cytokines associated with Th17/Th1 response such as IL-6, TNF-α, and IL-1β, and neutrophil-recruiting chemokines including CCL2, CCL3, CXCL1, and CXCL2 were highly produced from day 3 to day 14 after WT infection." (PMID 35696422, 2022). "Plasma levels of mast cell protease 1 (MCPT-1) and CCL2 were increased in either AnxA1 and FPR2 KO animals compared to their respective controls after infection." (PMID 35293862, 2022). "After 48 h of infection, the levels of TNF, CXCL8, IL6, CSF2, CD180, CD14, and CCL2 levels increased and those of IL-10, INFB1, and CXCL10 decreased." (PMID 36296238, 2022). "Monocyte chemoattractant protein-1 (MCP-1)/chemokine (C-C motif) ligand 2 (CCL2) plays important roles in regulating monocyte/macrophage migration and recruiting monocytes to the site of inflammation after tissue damage or infection." (PMID 35022045, 2022). "CCL2 is the primary ligand for CCR2, and it recruits macrophages to a variety of injury and infection sites." (PMID 35820932, 2022). "In summary, we here show that an infection with IAV H1N1 in mice induced by minor clinical manifestations that were accompanied by an early and reversible reduction of plasma CCL2 levels." (PMID 36365071, 2022). "The first days of infection were characterized by a higher production of CCL2/MCP-1 and CXCL10/IP-10, which decreased as the infection progressed." (PMID 35456119, 2022). "Various inflammatory cytokines such as TNF (TNF), some ILs (IL1α, IL1β), and chemokines (including CCL2, CCL4, CCL5, CXCL8) were significantly up-regulated under all observation points after YC-2020 infection." (PMID 36338035, 2022). "Secondly, virulent mycobacteria (such as M. marinum) exploit a unique lipid effector, phenolic glycolipid (PGL), to secrete CCL2, a chemokine ligand for CCR2, which recruits permissive macrophages to the infection site in a STING–CCL2–CCR2-dependent manner." (PMID 35603185, 2022). "To this extent, we analyzed lung homogenates for the expression of Ccl2 and Ifnb1, and compared the data from co-infected mice to GAS mono-infection or uninfected controls." (PMID 36365071, 2022). "Proinflammatory cytokines and chemokines analyses in the BAL showed that VACV∆C7L infection resulted in the release of IFN-γ, IL-6, CCL2, CXCL10, and CXCL9 into the BAL." (PMID 35351885, 2022). "Quantitative real-time PCR analysis of key inflammatory mediators demonstrated that SARS-CoV-2 (MA10) infection elevated cytokine IL-6 in BLAB/c and chemokine Ccl2 expression in Rag2−/− mice in comparison with mock-treated mice." (PMID 36680154, 2022). "Proteins highlighted in green (e.g., CCL2=MCP-1, CCL7=MCP-3, CCL8=MCP-2, CXCL10=INP10, are proteins known to be elevated in blood after infection for example with M. tuberculosis." (PMID 35145507, 2021). "Analysis of cytokine and chemokines in serum showed a characteristic peak in IL-6, CCL2, CXCL10, and CXCL11 production at day 1 after virus inoculation as also described by others for H5N1 and pH1N1 infection." (PMID 33671829, 2021). "The avian H7N9 (H7/SH2/13) also can infect human neurons and astrocytes cell lines, and thus the infection results in the increase of IL-6, IL-8, TNF-α, IFN-β, and CCL2." (PMID 33917837, 2021). "We observed increased levels of CXCL1, CCL2 and TNF-α in the spleens of Δisp2-infected mice after 4 days of infection." (PMID 34153047, 2021). "Several chemokines potentially attract neutrophils during an infection and S. suis infection induces the production of many of them, such as CXCL1 (KC), CXCL2 (MIP-2), CCL2 (MCP-1), CCL3 (MIP-1α), CCL4 (MIP-1β) and CCL5 (RANTES)." (PMID 34835517, 2021). "In contrast, levels of MCP-1/CCL2, NGAL, sTNFRSF1A, CXCL9, MMP-9, lactoferrin, and IL-1α did not significantly change in patients between critical disease in the ICU and upon infection recovery post-ICU." (PMID 33232303, 2021).
infection (continued). "On the other hand, this inflammatory response was more efficiently regulated in the later stages of the infection, as evidenced by decreased levels of neutrophils, TNF-α, CCL2, and IL-6 and the increases in the regulatory cytokines IL-10 and IL-27." (PMID 34207076, 2021). "A pronounced innate immune response to infection followed the peak of viral replication, evidenced by induction of cytokines (IL‐6, TNF), chemokines (CCL2, CCL5) and type I and III IFNs (IFNβ, IFNλ1/3) measured by RT–qPCR (and EV2D–F)." (PMID 34101213, 2021). "We showed that infection occurred in HSF cells and increased gene expression and protein secretion of two major proinflammatory CCL-2 and IL-1β markers." (PMID 33737658, 2021). "CCL2 remains downregulated (>2 log2 fold) early in both HTNV and ANDV infection (6 hpi to 4 dpi) and remained downregulated (>2 log2 fold) from 8 dpi through the remainder of the tested timepoints." (PMID 34339406, 2021). "Both CCL2 and CCL20 are myeloid chemo-attractants that alert other immune cells to the site of infection." (PMID 34943923, 2021). "Among the most notable differences were IL-6, CCL2, and CXCL10 (IP-10), at 4.1-, 2.3- and 2.1-fold higher levels, respectively, than those detected in response to the sublethal PVM infection." (PMID 33922096, 2021). "There was induction of a variable cytokine response in respiratory tissues at different days post-infection (dpi), including TNF-α, IFN-β, IL-4, IL-6, CXCL8 (IL-8), IL-10, IL-13, CXCL10 (IP-10), CCL5 (RANTES), CXCL9 (MIG), and CCL2 (MCP-1)." (PMID 34452505, 2021). "Inhibition of miR-548d-3p reduced parasite growth early after infection and increased production of MCP1/CCL2, RANTES/CCL5, and IP10/CXCL10." (PMID 34178725, 2021). "Both CCL2 and CCL3 mRNA levels were elevated by almost 1000-fold on days 5 and 6 after infection consistent with the high level of virus in the brain." (PMID 33477869, 2021). "This study showed that early infection samples have high levels of IL-8 and CCL-2/MCP-1 in serum as compared to sera from uninfected controls." (PMID 34088327, 2021). "C. albicans GDH18 infection led to enhanced mRNA expression levels of Dectin-2, TLR2, CCL2, and CXCL1/KC, compared with the levels in uninfected mice." (PMID 33919079, 2021). "The results of IL-6, CCL2 and CXCL10 secretion from OT-infected HMECs at 8, 16, 24, and 48 hours post-infection were shown in." (PMID 34368012, 2021). "L. rhamnosus L8020 treatment significantly reduced the expression levels of Dectin-2 and CCL2, and tended to reduce the expression levels of TLR2 and CXCL1/KC, following infection by C. albicans GDH18." (PMID 33919079, 2021). "Next, we defined proinflammatory macrophages as cells expressing high levels of CCL2 and CCL3, chemokines involved in recruitment of adaptive and innate cells to sites of infection, and which were also characterized by the expression IL6, IL1B, and TNF." (PMID 33622974, 2021). "We confirmed that levels of CCL2 protein in lung tissue and BALF increased after infection, peaking at 5 dpi, the time of maximal pre-cDC influx." (PMID 34739343, 2021). "It is worth noting that a very early (i.e. 24-48 h p.i.)but transient expression of CCL2 and CXCL1 has also been reported upon infection by RSV, CMV and influenza virus." (PMID 33858301, 2021). "Suggesting low systemic response, the blood of mice trained 9 weeks contained lower levels of a broad range of cytokines (IL-1β, IL-6, IL-10, IL-12p40, IL-17A, IL-18, IFNγ, TNF, CCL2 and CXCL5) 2 days after infection with L. monocytogenes." (PMID 34603295, 2021). "Mice given LVS IN have readily detectable MCP-1/CCL2 in vivo in lung homogenates within a week after infection, and splenocytes from mice infected with LVS ID produce MCP-1 ex vivo." (PMID 33760886, 2021). "Neutrophils provide the chemical cues (MCP-1/CCL2, MIP-1α/CCL3, MIP-1β/CCL4 and MIP-2/CXCL2) that help recruit macrophages to the infection site." (PMID 34712235, 2021).
infection (continued). "BothCCL2 and CCL7 and their receptors were downregulated.CCL2 and its receptors, CCR2 andCCR4, act to recruit monocytes and macrophages to the site of infection.The majority of chemokines were significantly up-regulated." (PMID 32347041, 2021). "We therefore used qPCR to measure CCL2 and IL-8 expression in A549-ORF7 and control cells following infection by these viruses." (PMID 34603560, 2021). "Nevertheless, the RNA levels of IL-6, CCL2 and CXCL10 decreased after 5 days of infection, especially IL-6 that went down with more than 5-fold reduction compared to that on day 2 post infection." (PMID 34379705, 2021). "Protection against lethal infection; reduced granulocyte recruitment; reduced expression of proinflammatory cytokines CXCL10, CXCL1, CCL2, and TNF." (PMID 34557097, 2021). "Within 12 days of infection, cytokine expression progressed from continuous macrophage activation (IFN-α/β, CCL2, IFN-γ), to pro-inflammatory (IFN-α/β, IL-6, IFN-γ), and finally to infiltration (CCL2)." (PMID 34790202, 2021). "At 24 h post-infection, serum levels of IL-6, IL-17A, TNF-α, and IFN-γ were greatly reduced in IL-38-treated group, CCL2 and CXCL10 decreased at day 4, IL-1β and CCL-5 decreased on day 7 in the IL-38-treated group compared with group without IL-38 treatment." (PMID 33414457, 2021). "Despite the differences in the magnitude of induction between each HBEC donor, combined, we observed a consistent trend of proinflammatory cytokine and chemokine (CCL2, CCL20, CXCL6, IL-6 and TNFα) inductions within 24 h post-infection with SARS-CoV-2." (PMID 34452468, 2021). "As mentioned, we found that the expression of CXCL1, CXCL12, CCL2, CCL5 and TIMP-1 was significantly increased upon CGS-17 and CXZ-15 infection." (PMID 33081802, 2020). "In the mouse brain, pericytes function as the initial sensor of systemic inflammation and relay the infection signal to neurons by secreting chemokine CC chemokine ligand 2 (CCL2, also known as monocyte chemotactic protein-1, MCP1)." (PMID 32317958, 2020). "Levels of IL-1β, IL-6, CCL2, CCL3, CXCL1, and CXCL2 were significantly greater 6 h following infection than in mock-infected mice (P < 0.05) but were similar among wild-type, CCR2−/−, and Nr4a1−/− mice." (PMID 31818962, 2020). "For example, high levels of CXCL-10/IP-10, CCL-2/MCP-1, CXCL-5/RANTES, and CCL-3/MIP-1α enhance the recruitment of dendritic cells and macrophages to the site of infection." (PMID 32922406, 2020). "In fibroblasts the infection produces IFN-β, tumor necrosis factor-α (TNF-α), interleukin-4 (IL-4), IL-1-β, chemokine (C-C motif) ligand 2 (CCL2), and chemokine (C-C motif) ligand (CCL5)." (PMID 31979145, 2020). "Unexpectedly, most SARS patients experience a robust upregulation of type-I interferon during the early phase of infection that occurs concurrently with an upregulation in the expression of IFN-stimulated chemokines (CXCL-10 and CCL-2)." (PMID 32922406, 2020). "Also, miRNAs that are deregulated during infection, such as miR-30e and miR-302d, interfere with Nos2 mRNA expression and NO production; miR-294 and miR-302d regulate Tnf mRNA levels and miR-294 alters Ccl2/Mcp-1 mRNA, implicating the expression of these miRNAs in controlling infectivity." (PMID 31906500, 2020). "C-C motif chemokine ligand 2 (CCL2; also known as monocyte chemotactic protein 1) specifically recruits monocytes to the sites of inflammation, infection, or trauma." (PMID 32809188, 2020). "We found that the expression of CCL2, CCL5, IL-6, and TNF-α was inhibited through the course of infection in U0126-pretreated cells and that viral RNA abundance was also decreased in U0126-pretreated cells." (PMID 31694957, 2020). "Several chemokines, including IP-10 (CXCL10), CCL2 (MCP-1), CCL3 (MIP-1α), CCL4 (MIP-1β), CCL5 (RANTES), and CCL7 (MCP-3) were also significantly increased upon infection." (PMID 32373101, 2020).